VIM (vimentin)
Diseases named in the same sentence as VIM in open-access papers (continued):
Sharing a sentence is not in itself a finding about the gene and the disease.
prostate carcinoma (continued). "We experienced that both Vimentin and E-cadherin were detectable in PC-3 cells under several culture conditions, suggesting that prostate cancer cells could often have a E/M hybrid status." (PMID 36552758, 2022). "A recent study has also shown that the LIM domain only 2 (LMO2, a key regulator of hematopoietic stem cell development) is transcriptionally repressed by AR in prostate fibroblasts and that LMO2 is elevated in primary human prostate cancer vimentin+/αSMA+ CAFs in response to enzalutamide treatment." (PMID 36671452, 2022). "To examine whether the prostate cancer cell migration and invasion were associated with the EMT, we detected the expression of EMT related proteins, including MMP-2, vimentin and E-cadherin in PC-3 and DU145 cells." (PMID 33613773, 2021). "Another exosomal miRNA, miR-1246, was found to be downregulated in prostate cancer cells, but was found to inhibit tumor growth in vivo while inhibiting N-cadherin and vimentin levels in vitro, suggesting a protective role against disease progression for this miRNA." (PMID 33672595, 2021). "For instance, Withaferin-A, a natural bioactive compound, has been shown to induce apoptosis against vimentin-expressing cancer cells, while Silibinin can result in the downregulation of vimentin and metalloproteinase-2, thereby reducing prostate cancer cell invasion and motility." (PMID 31963677, 2020). "Vimentin is overexpressed in the highly invasive prostate cancer cell line CL1." (PMID 32670437, 2020). "We examined TrampC1 and RM1 after treatment with the fibroblast-conditioned medium and found that the expression of E-cadherin was decreased in the prostate cancer epithelial cells and that the expression of N-cadherin and vimentin was increased due to the upregulation of YAP1." (PMID 32066485, 2020). "Consistent with this hypothesis, histone deacetylase inhibitors increased EMT markers, including ZEB1, TWIST1, and vimentin in prostate cancer cells." (PMID 31101737, 2019). "Furthermore, Western blot analysis reveals that HDGF knockdown inhibits epithelial-mesenchymal transition (EMT) of prostate cancer cells by upregulation of protein E-cadherin and downregulation of proteins N-cadherin, Vimentin, Snail and Slug." (PMID 29300772, 2018). "Vimentin staining was used to distinguish prostate cancer cells from host cells." (PMID 29717114, 2018). "This suggested that vimentin expression in prostate cancer results in high tumorigenic activity." (PMID 30248895, 2018). "Some studies showed that vimentin transfected cells showed more vimentin expression and less E-cadherin expression and furthermore led to a significant increase in prostate cancer cells motility and invasive activities resulting in distant pulmonary metastasis." (PMID 28108731, 2017). "E-Cadherin was also reduced in DU145/XB130- and LNCap/XB130- associated with enhancement of vimentin expression, indicated that XB130 may promote migration and invasion of prostate cancer through mediating EMT by activating PI3K/Akt." (PMID 27509056, 2016). "Moreover, we recently identified a set of 74 early genes including VIM (the gene encoding vimentin) that are up-regulated in a LPA1-dependent manner in breast and prostate cancer cells stimulated with LPA (GEO Series accession number GSE56265)." (PMID 26098771, 2015). "In summary, miRNAs 200b, 30a, 1, and 183 and the genes Twist1 and Vimentin might play important roles in the progression of prostate cancer and may eventually become important prognostic markers." (PMID 25409297, 2014). "We examined whether plectin and vimentin contribute to cell proliferation in prostate cancer using the RNAi technique." (PMID 23717685, 2013). "To determine whether plectin and vimentin are involved invasion and migration and thus potentially prostate cancer metastasis, we transfected PC3-ML2 with siRNA targeting the two genes." (PMID 23717685, 2013).
prostate carcinoma (continued). "In summary, we have identified several proteins including plectin and vimentin that may act as markers for prostate cancer disease progression." (PMID 23717685, 2013). "Poorly differentiated prostate tumors also showed higher expression of vimentin, a cytoskeletal component responsible for maintaining cell integrity, and high levels of vimentin correlated with the invasive capacity of prostate cancer cell lines, including DU145." (PMID 22328933, 2012). "Inhibition of vimentin expression has been shown to change prostate cancer cell morphology leading to reduced tumor growth in vivo, and thus increased expression of vimentin is expected to have aggressive tumor cell behavior as supported by our results presented in this manuscript." (PMID 23024790, 2012). "Blockage of NF-κB is positively correlated with the suppression of vimentin expression and inhibition of the invasive phenotype of prostate cancer cells, suggesting that EMT may be used as a predictor of certain cancers." (PMID 22536447, 2012). "Moreover, we were able to demonstrate that surface vimentin is co-expressed on the surface of three different metastasis-derived prostate cancer cell lines with CD44 and CD133 molecules." (PMID 24212937, 2011). "We propose that surface vimentin could be such a common marker of highly metastatic cancer cells and as well possibly related to prostate cancer stem- or progenitor cells." (PMID 24212937, 2011). "We found that surface vimentin is detectable on the metastases-derived prostate cancer cells." (PMID 24212937, 2011). "In addition, flow cytometric analysis revealed that vimentin expression was readily detected along with CD44 expression but only a small subpopulation of prostate cancer cells expressed vimentin and the putative stem cell marker CD133 along with CD44." (PMID 24212937, 2011). "However, more rigorous proof of internalization is still required as is the specific requirement of vimentin expression for the prostate cancer lines." (PMID 24212937, 2011). "For example, in prostate cancer cells, expression of KLK3 and KLK4 results in loss of E-cadherin and induction of expression of the mesenchymal marker vimentin, a hallmark of epithelial-to-mesenchymal transitions, which is a critical step for cancer metastasis." (PMID 21072173, 2010). "In prostate cancer cells, the level of vimentin expression has been correlated with cell motility, and the majority of poorly differentiated cancers and bone metastases showed high vimentin expression in tumor cells." (PMID 21317457, 2010). "Indeed, vimentin filaments are expressed by undifferentiated prostate cancer cells." (PMID 34768368, 2021). "Western blotting assay further indicated that CCL5 could induce epithelial-mesenchymal transition (EMT) in both prostate cancer cells, characterized by the decreased expression of E-cadherin as well as the increased expression of N-cadherin, Vimentin, MMP2, and MMP9." (PMID 32300100, 2020). "In addition, GA-treated prostate cancer cells also caused the induction of EMT-TFs (twist, snail, and slug) and vimentin expression in conjunction with a concomitant decrease in the expression of the E-cadherin that was observed in three prostate cancer cell lines." (PMID 31060254, 2019). "To control for the possibility that the predictive power of the gene signature reported here may be affected by variation in stromal content of the prostate cancer specimens, we assessed the mRNA expression of two stromal markers, smooth muscle alpha-actin and vimentin, in our validation set." (PMID 27966447, 2017). "Additionally, the isolation of purely mesenchymal tumor cells from a model of prostate cancer shows that these Vimentin positive cells showed reduced capacity to form metastatic lesions upon tail vein injection when compared with their Vimentin negative counterparts." (PMID 26274893, 2015).
prostate carcinoma (continued). "Finally, Cowpea mosaic virus (CPMV) nanoparticles that target vimentin could bind and internalize into tested prostate cancer cell lines." (PMID 24212937, 2011). "In addition, expression levels of some genes associated with the progression of prostate cancer, such as relaxin, vascular endothelial growth factor (VEGF), vimentin and bone morphogenetic protein-6 (BMP-6), were significantly downregulated in LNCaP/IL-6#1 compared with LNCaP/Co." (PMID 19844233, 2009). "Vimentin and RAD51 expression also showed a trend to positively correlate, in line with the fact that RAD51 is coupled with EMT in breast and prostate cancer." (PMID 40456663, 2025). "We used vimentin (and intracellular and extracellular collagen) to confirm cCAFs phenotype which is shown to be expressed among the different CAF subsets in prostate cancer." (PMID 38634185, 2025). "Prostate cancer in an EMT-like state exhibits changes in marker expression, such as E-cadherin and vimentin." (PMID 39301540, 2024). "Here, we have identified VIM as a top common EMT marker from RNA-seq and scRNA-seq for aggressive prostate cancer subtypes." (PMID 37476073, 2023). "Among different subgroups in prostate cancer scRNAseq data, significant correlations between EMP1/COL3A1 and four EMT genes (VIM, SNAI2, TWIST1, and CTNNB1) were found in the osteoblast subgroup." (PMID 38187400, 2023). "Our in vitro results showed BUD31 knockdown promotes cell proliferation and migration of prostate cancer cells via activation of p-AKT and vimentin." (PMID 37047027, 2023). "In contrast, CAV2 induces various epithelium-related molecules, including Vimentin, N-Cadherin, E-Cadherin, MMP13, and MYCL, which play important roles in prostate cancer cell motility." (PMID 35517414, 2022). "Our bioinformatics analysis from TCGA dataset showed, for prostate cancer tissues, a positive correlation of mRNA expression of MYH9 with mRNA expression of GSK3β, β-catenin, cyclin D1, c-MYC, vimentin, and N-cadherin." (PMID 35589707, 2022). "Numerous studies have shown that ADT can result in an increase in expression of mesenchymal markers such as vimentin, N-cadherin and TWIST1, and a decrease in epithelial markers, especially E-cadherin, in prostate cancer PDX model and patient tumours." (PMID 35493092, 2022). "Overexpression of RHAMM in prostate cancer cells increased phosphorylation of ROCKII and coflin with an accompanying increase in filopodia formation and EMT markers, vimentin and N-cadherin, and a decrease in E- cadherin." (PMID 36033439, 2022). "This analysis revealed a striking positive correlation between the expression of PKCα (PRKCA gene) and mesenchymal markers vimentin, ZEB1, ZEB2, and AXL in prostate cancer cell lines." (PMID 36818489, 2022). "Recently, it was reported that miR-182 overexpression upregulated EMT-related genes, such as N-cadherin, vimentin, and ZEB1, but downregulated E-cadherin expression in prostate cancer cells." (PMID 36293154, 2022). "Accordingly, DDR1 activates EMT via stimulating the protein expression of N-cadherin and vimentin and phosphorylation of Pyk2 and MKK7 in prostate cancer." (PMID 35267698, 2022). "Above data demonstrates that both PKC-ι and PKC-ζ are responsible for the phosphorylation of Vimentin in multiple phosphorylation sites and thereby controls the VIF dynamics in prostate carcinoma." (PMID 33525953, 2021). "In prostate cancer, UBE2T mediated the proliferation and epithelial-mesenchymal transition (EMT) of prostate cancer cells by regulating vimentin." (PMID 34257599, 2021). "Taken together with the reduction of Vimentin expression and upregulation of E-cadherin, these results further confirmed the diminution of EMT in prostate cancer cells." (PMID 33525953, 2021). "This fragment reduces Vimentin promoter luciferase activity, membrane localization and intensity of AKT-PH domain upon EGF stimulation, focus formation and migration of prostate cancer cells." (PMID 34706306, 2021).
prostate carcinoma (continued). "Results suggest that aPKCs target multiple activation sites (Ser33/39/56) on Vimentin and therefore is essential for VIF dynamics regulation during the metastasis of prostate cancer cells." (PMID 33525953, 2021). "The role of Qu in prostate cancer is reported through the regulation of EFGR signaling and other molecules (e.g., cell adhesion, such as vimentin, N-cadherin, and E-cadherin)." (PMID 33804548, 2021). "Poorly differentiated tumours also had lower expression levels of E-cadherin and higher levels of vimentin, suggesting the ongoing EMT of prostate cancer cells." (PMID 30952903, 2019). "The data showed that the presence of VM and high ZEB1 expression was associated with higher Gleason score, TNM stage, and lymph node and distant metastases as well as with the expression of vimentin and CD133 in prostate cancer tissues." (PMID 29754422, 2018). "PP2 treatment also significantly reduced the expression of VE‐cadherin, vimentin and CD133 in these prostate cancer cells." (PMID 29754422, 2018). "To explore the mechanism underlying EMT and hypoxia-induced docetaxel resistance due to HIF-1α overexpression in prostate cancer cells, we knocked down HIF-1α and examined E-cadherin and vimentin expression using western blotting." (PMID 29568752, 2018). "RANKL becomes overexpressed in parallel with vimentin and N-cadherin during TGF-beta-induced EMT in prostate cancer cell lines." (PMID 28977822, 2017). "Additionally, TSA also led to prostate cancer aggressiveness via induction of epithelial-to-mesenchymal transition phenotype which associated with increased expression of transcription factors ZEB1, ZEB2 and Slug, and mesenchymal markers such as vimentin, N-cadherin and fibronectin." (PMID 28785170, 2017). "We found a reduction in NF-κB (p65), IL-1β, and Vimentin and upregulation of E-cadherin protein levels in MTA1 knockdown (shMTA1) prostate cancer cells, suggesting direct involvement of MTA1 in inflammation and EMT in prostate cancer." (PMID 26943043, 2016). "In vitro, IL–20 upregulated N-cadherin, STAT3, vimentin, fibronectin, RANKL, cathepsin G, and cathepsin K, and increased the migration and colony formation of prostate cancer cells via activated p38, ERK1/2, AKT, and NF-κB signals in PC–3 cells." (PMID 26440411, 2015). "Our study demonstrates that miR-940 completely inhibits this ability of prostate cancer cells along with promoting MET by increasing the E-cadherin and decreasing Vimentin expression." (PMID 25406943, 2014). "For example, it was demonstrated that various prostate cancer cell lines like DU145, LNCaP and PC3 expressed two different domains of vimentin at the surface." (PMID 24967582, 2014). "The CTCs identified with GLV-1h254 in mice bearing human PC-3 prostate cancer xenografts displayed high levels of the expression of the CSC markers CD44 and aldehyde dehydrogenase 1 (ALDH1) as well as the EMT markers vimentin and N-cadherin." (PMID 24019862, 2013). "Surface vimentin was found to be co-expressed on a subpopulation of cells along with CD44 and CD133 suggested to be markers of prostate cancer stem cells." (PMID 24212937, 2011). "Furthermore, the KM plotter and GEPIA results demonstrated that when prostate cancer progresses, there are changes in the expression of CDH1, CDH2, VIM, SNAI1, ZEB1, and ZEB2." (PMID 40693059, 2025). "Prostate cancer cells with FTO knockout were pretreated with CHX and MG-132 for 6 h and then treated with or without 10 ng/ml TGF-β for 48 h, followed by the detection of METTL3 and vimentin expression using western blot analysis." (PMID 38384328, 2024). "The increase of miR-139–5p greatly inhibits the expression of SOX5 in prostate cancer cells, down-regulates TWIST, and reduces the expression of N-cadherin and vimentin, thereby inhibiting the EMT process and thus inhibiting the cell proliferation and cell migration of prostate cancer cells." (PMID 38835366, 2024).
prostate carcinoma (continued). "Furthermore, SNAI1 plays a critical role in the aggressiveness of prostate cancer by increasing the expression of CD44 and vimentin." (PMID 37476073, 2023). "In contrast, circAMOTL1L is downregulated in human prostate cancer, and reduced circAMOTL1L facilitates the migration and invasion of prostate cancer cells by downregulating E-cad and upregulating vimentin, thereby leading to EMT and prostate cancer progression." (PMID 37020791, 2023). "It appears that CRISP3 may foster prostate cancer proliferation and migration by promoting EMT, as evidenced by the suppression of N-cadherin, Vimentin, and Snail markers of EMT after knocking down hsa_circ_0003823 protein." (PMID 37070095, 2023). "Furthermore, the relative phosphorylation of eEF2 at T56 in DU145 prostate cancer cells was less affected by treatment of TGF-β1 even in the presence of CQ and consequently Vimentin was similarly expressed in response to TGF-β1." (PMID 36230768, 2022). "Use of the V9 human-specific VIM antibody enabled identification of human prostate cancer cells and not other murine mesenchymal cells that would also be VIM+." (PMID 34206049, 2021). "Similarly, silencing CKB in 2 other prostate cancer cell lines DU145 and VCaP reduces E-cadherin and induces Vimentin." (PMID 34706306, 2021). "Finally, this new model can be used to develop more specific and effective therapeutics for advanced prostate cancer patients based on PKC-ι/ζ and Vimentin." (PMID 33525953, 2021). "Employing siRNA-based partial target modulation in DU145 and PC3 prostate carcinoma cells, inhibition of EMT-related gene expression (with downregulation of MMP9, MMP2, VIM, and SNAI1, among others) and suppression of migration and metastasis were assessed in vitro." (PMID 32466621, 2020). "Also, linear regression analysis showed a significant correlation between 18F–choline uptake and the number of vimentin, RANKL, VDR, or PTX3 positive prostate cancer cells." (PMID 31614564, 2019). "Noteworthy, more than 90% of lesions with no/rare vimentin-positive prostate cancer cells showed very low uptake of choline." (PMID 31614564, 2019). "Furthermore, inhibition of GPC-1 decreased several markers of prostate cancer aggression, such as MMP-9, E-Cadherin (E-Cad), N-Cadherin (N-Cad), CXCR4, vimentin (VIM), Zeb1 and Zeb238–40, as determined using qRT-PCR." (PMID 31391540, 2019). "Analysis of the expression of vimentin, which contributes to prostate cancer invasiveness, indicated that tumors in which FZD8 was silenced exhibited lower levels of vimentin than control tumors, consistent with the role of FZD8 in prostate tumor cell invasion." (PMID 29717114, 2018). "Of note, immunostaining for vimentin distinguishes prostate cancer cells from CAM cells, which are negative for this marker." (PMID 29717114, 2018). "This study revealed that EBAG9 modulates the expression of EMT-related genes containing VIM, SNAI1, and SNAI2 in prostate cancer cells, suggesting that EBAG9 could stimulate cancer progression and invasion through EMT pathway." (PMID 29362448, 2018). "It has been shown that quercetin can prevent cell migration and epithelial-mesenchymal transition by suppressing the expression of N-cadherin and vimentin in prostate cancer cell lines with no cytotoxic effect on normal prostate epithelial cells." (PMID 29163752, 2017). "We found three groups of genes in the EMT differentially expressed list: a) known EMT genes (e.g. CDH1, ZEB1, TGFB, CDH2, VIM, TIMP1), b) EMT genes previously unknown in prostate cancer (LSR, S100A14, DPYSL3) and c) novel EMT genes (including C1orf116)." (PMID 28651527, 2017). "We and others have observed significant vimentin expression within PBMC cell populations; consequently, we used TaqMan assays targeting EpCAM and ARHGAP29 transcripts for specific identification of prostate cancer cells." (PMID 27189161, 2016).